VSIG10L (V-set and immunoglobulin domain containing 10 like)
Tractability: Antibody: UniProt predicts a signal peptide or a membrane-spanning region.
Gene: Protein-coding gene on chromosome 19 (51,331,536 to 51,342,310, reverse strand). Ensembl gene ENSG00000186806.
Subcellular location: Membrane
Subcellular location (Human Protein Atlas): Nucleoplasm
Gene Ontology:
Cellular component: membrane
Genetic constraint (gnomAD): Loss-of-function variants: 63 observed, 61.22 expected, observed/expected ratio (o/e) 1.03, 90% interval 0.84 to 1.27. The upper end of that interval is the gene's LOEUF score, 1.27, which puts it in group 5 of 6, group 1 being the genes least tolerant of losing a copy. Missense variants: 1,043 observed, 1,031.3 expected, observed/expected ratio (o/e) 1.01, 90% interval 0.96 to 1.06. Synonymous variants: 497 observed, 450.56 expected, observed/expected ratio (o/e) 1.1, 90% interval 1.02 to 1.19.
Homologues: Orthologues: chimpanzee VSIG10L (97% identical), macaque VSIG10L (95% identical), dog VSIG10L (77% identical), pig VSIG10L (76% identical), rat Vsig10l (71% identical), mouse Vsig10l (69% identical), guinea pig VSIG10L (67% identical). Paralogues in human: IGSF10 (20% identical), MXRA5 (20% identical), HMCN2 (18% identical), CNTN3 (18% identical), CNTN2 (17% identical), ROBO3 (17% identical), SDK2 (17% identical), CNTN5 (17% identical), NRCAM (17% identical), ROBO1 (17% identical), SDK1 (17% identical), CNTN6 (16% identical), and 24 more.
Diseases named in the same sentence as VSIG10L in open-access papers:
VSIG10L is named in the same sentence as 3 diseases in open-access papers, as found by Europe PMC text mining. Sharing a sentence is not in itself a finding about the gene and the disease. The quoted sentences say what the papers report.
cholestasis (1 paper, 2023). Impairment of the bile flow caused by obstruction within the liver, or outside the liver in the bile duct system. "The putative functions of two less investigated genes (i.e., SLC16A3 and VSIG10L) were found to correlate with previously discovered key events involved in the development of cholestasis, specifically bile flow disruption, and autophagy." (PMID 37603094, 2023).
cancer (1 paper, 2023). A tumor composed of atypical neoplastic, often pleomorphic cells that invade other tissues. "VSIG10L is a poorly characterized gene, but studies have indicated a dual nature of its expression in relation to cancer development." (PMID 37603094, 2023). "However, the exact role of VSIG10L in cancer development or other diseases and its transcriptional changes remains unclear." (PMID 37603094, 2023).
VSIG10L also shares sentences with these, for which no sentence is quoted: tumor (1 paper).